ARID1A (AT-rich interaction domain 1A)
Diseases named in the same sentence as ARID1A in open-access papers (continued):
Sharing a sentence is not in itself a finding about the gene and the disease.
cancer (continued). "A previous study reported that ARID1A activity was correlated with p-AKT signals in cancers, and the key components of the phosphatidylinositol 3-kinase (PI3K) pathway were often either mutated or dysregulated in SCLC." (PMID 41049615, 2025). "ARID1A‐deficient tumors are associated with high TMB and a more favorable prognosis in response to immunotherapy across multiple human cancers." (PMID 41387924, 2025). "AT-rich interaction domain 1A (ARID1A), is frequently mutated in cancer, leading to loss-of-function and posing challenges to therapeutic targeting." (PMID 41215803, 2025). "We performed an in vitro validation of predicted target pairs miR-129-5p/ARID1A and miR-3613-3p/ARID1A in cancer cell lines." (PMID 39796161, 2025). "Downregulation of ARID1A not only promotes cancer cell proliferation but also contributes to metastatic potential and increased genomic instability." (PMID 40429787, 2025). "One area of interest in low ARID1A-expressing cancer cells is the impairment of its mismatch repair function." (PMID 40429787, 2025). "Understanding ARID1A’s multifaceted roles offers a compelling lens through which to explore chromatin dysregulation in cancer and guide translational advances." (PMID 40429787, 2025). "Fourth, ARID1A‐depleted cancer cells are more sensitive to the enhancer of zeste homolog 2 methyltransferase (EZH2) inhibitors because ARID1A and EZH2 are functionally antagonistic in the control of gene expression." (PMID 40621620, 2025). "Loss of ARID1B is synthetically lethal in ARID1A-deficient cancer cells, suggesting that ARID1B is a therapeutic target in ARID1A-deficient cancers." (PMID 41017120, 2025). "One of the tested and verified alternatively spliced candidates, JMJD1C, is a histone demethylase that regulates DNA double‐strand break repair and is involved in tumorigenesis, linking ARID1A once more to cancer." (PMID 40170512, 2025). "Downregulation of ARID1A has generally been reported to be an independent prognostic factor for shorter cancer‐specific survival in NSCLC." (PMID 41387924, 2025). "While correlative human data can highlight the predicted phenotypes when ARID1A is lost, this review will also emphasize some of the mechanistic studies performed in mice and other cancer models." (PMID 40429787, 2025). "Among these subunits, AT-rich interactive domain-containing protein 1A (ARID1A) is the most frequently mutated gene, occurring in over 8% of various cancers." (PMID 41017120, 2025). "ARID1A-mutant cancers are particularly sensitive to EZH2 inhibition (e.g., GSK126), an effect linked to the suppression of PI3K/AKT signaling." (PMID 41514650, 2025). "Here, we demonstrated that targeting the ATR/CHK1 axis triggers cancer cell-intrinsic immunogenicity by the STING-mediated DNA-sensing pathway to enhance the therapeutic efficacy of radiotherapy and ICBs in ARID1A-deficient tumors." (PMID 40750787, 2025). "The loss of ARID1A activates Annexin A1, which aligned closely with a region targeted by EBV-associated cancers on chromosome 9." (PMID 39885374, 2025). "As we understand more about the molecular mechanisms of ARID1A in different cancers, we can exploit the vulnerabilities therapeutically." (PMID 40429787, 2025). "Analysis of ARID1A expression across 33 cancer types revealed robust correlations with four immune modalities: immunosuppressive genes, immunostimulatory genes, chemokines, and chemokine receptors." (PMID 41215803, 2025).
cancer (continued). "Analysis of data from the Cancer Cell Line Encyclopedia (CCLE) demonstrated a statistically significant inverse correlation between ARID1A and c-MYC expression levels at the transcriptional level." (PMID 41049615, 2025). "ARID1A is not only involved in various stages of cancer development but contributes to this through multiple hallmarks of cancer." (PMID 40429787, 2025). "ARID1A is known to support inflammatory signaling in adult cancers but its role in NB inflammatory signaling is unexplored." (PMID 40082458, 2025). "While ARID1A mutations are well-established in tumors, ARID1B mutations are also frequently reported in cancers, albeit with a lower frequency." (PMID 40342423, 2025). "The selective deletion of Arid1a in the pancreas of mice results in PanIN formation and accelerates cancer development when combined with the tissue-specific expression of mutant KrasK12D or with Pten deletion." (PMID 40723241, 2025). "Given the significant role of ARID1A in cancers, future comprehensive investigations into the structure and function of ARID1A will be crucial for developing effective treatment strategies for relevant tumors." (PMID 38761067, 2025). "This cluster contained mutations in representative cancer-associated genes such as KRAS, ARID1A, PIK3CA, and FBXW7." (PMID 40679511, 2025). "﻿siRNA knockdown of some of these genes resulted in increased transcription of the HERV‐H locus, including ﻿ARID1A, ﻿a core subunit of BAF chromatin remodeler complex whose mutational inactivation is broadly found in human cancers." (PMID 39992019, 2025). "PDEECs with MMR deficiency exhibit increased genomic instability, leading to the accumulation of mutations across various cancer-related genes, including PTEN, PIK3CA, and ARID1A." (PMID 40072110, 2025). "ARID1A, within the commonly deleted 1p36 region in NB, has a role in initiating inflammatory signaling in adult cancers by opening areas of chromatin to enable the transcription of type I T-helper signaling genes." (PMID 40082458, 2025). "In adenomyotic epithelium, we identified somatic mutations in cancer-associated genes such as KRAS (34.1%), PIK3CA (12.2%), ARID1A (12.1%), and FBXW7 (9.8%) with high mutant allele frequency." (PMID 40679511, 2025). "ARID1A deficiency can also lead to mismatch repair defects, replication stress, and genomic instability, making ARID1A-mutant cancers vulnerable to specific therapies, including PARP inhibitors, EZH2 inhibitors, BET inhibitors, and ATR inhibitors." (PMID 40429787, 2025). "For instance, clones with PTEN and ARID1A monoallelic loss are positively selected in normal tissue but far below the frequency observed in CRC, indicating additional selection in cancer." (PMID 39920335, 2025). "Recent studies have shown that targeting synthetic lethal partners of ARID1A uncovers selective vulnerabilities in ARID1A-mutant cancers, including inhibition of EZH2, ATR, PARP, and HDAC6." (PMID 40750787, 2025). "By mapping ARID1A’s functional impact onto the established hallmarks framework, we highlight its centrality in cancer biology and underscore opportunities for biomarker-driven strategies and targeted interventions." (PMID 40429787, 2025). "Given the association between ARID1A loss and MSI, ARID1A-mutant cancers are more likely to exhibit high neoantigen loads, making them potential candidates for immune checkpoint inhibitors." (PMID 40072110, 2025). "Mechanistically, ARID1A loss increases the phosphorylation level of MAP4 (microtubule-associated protein 4), which is a key microtubule dynamics regulator in cancer cells." (PMID 41360780, 2025). "Recent molecular analyses have demonstrated that in mixed tumors, the YST and carcinoma components can harbor shared somatic mutations, including CTNNB1 and ARID1A, implying a common clonal origin and supporting the theory of somatic derivation." (PMID 41510478, 2025).
cancer (continued). "The combination of radiotherapy either with DDRi and/or immunotherapy in cancer patients with low ARID1A expression is a promising therapeutic approach to improve treatment response of cancer patients." (PMID 38587186, 2024). "U2-OS and SJSA-1 were selected based on their relative expression of Arid1a mRNA obtained from the cancer cell line encyclopedia (CCLE) database search." (PMID 39123453, 2024). "While ARID1A-BAF has a wide-range of roles including regulating aberrant chromatin accessibility in cancer contexts, its function in physiological craniofacial development is underappreciated." (PMID 39226899, 2024). "This dual role underscores the importance of ARID1A in maintaining the normal functioning of cells and protecting against the development of cancer by regulating cell cycles and preserving genomic integrity." (PMID 38391958, 2024). "Endometriotic lesions also harbour cancer driver mutations such as PIK3CA, PTEN, ARID1A, KRAS, PPP2R1A, and β-catenin (CTNNB1)." (PMID 38893278, 2024). "AT-rich interaction domain protein 1A (ARID1A), a SWI/SNF chromatin remodeling complex subunit, is frequently mutated across various cancer entities." (PMID 38587186, 2024). "ARID1B is a SWI/SNF subunit frequently mutated in human Coffin–Siris syndrome (CSS) and it is necessary for proliferation of ARID1A mutant cancers." (PMID 38347147, 2024). "Here, we analyzed 3 publicly available RNA-sequencing datasets that reflect gene expression changes between ARID1A-depleted and control cancer cells." (PMID 38229120, 2024). "Mutations, down-regulation of expression, and deletion of the ARID1A gene can predict drug resistance and recurrence in various cancers." (PMID 39697230, 2024). "This analysis revealed that transcript levels from KEAP1 inversely correlated with ARID1A, albeit mildly, across a pan-cancer panel (n = 10,071, r = −0.12, p = 2.2 × 10−16)." (PMID 39272807, 2024). "Several studies on cancer cell lines demonstrated that ARID1A inhibition promotes the migration and invasion of neoplastic cells, inhibits apoptosis, and induces angiogenesis." (PMID 38893181, 2024). "Others found that somatic genomic alterations of ARID1A and other genes, combined with TMB, were associated with the development of metachronous cancers after curative endoscopic submucosal dissection and successful HP eradication in EGC." (PMID 39028418, 2024). "ARID1A and ARID1B are components of the SWI-SNF complex that are involved in chromatin remodeling and are implicated in several human cancers." (PMID 38232086, 2024). "These EVs, produced by virus-infected cancer cells, carry artificial miRNA (amiR-4), which targets and suppresses genes like ARID1A that contribute to cancer cell resistance against viral infections." (PMID 39852137, 2024). "EGFR, IDH1, ARID1A, and CIC also displayed two associations each, while the remaining 68 hotspots corresponded to one gene associated with one specific cancer type." (PMID 38473427, 2024). "It is interesting to note that Arid1a NS mutations were detected in all cardiac schwannomas and 41% of these were orthologous to COSMIC variants associated with a variety of human cancers." (PMID 38232086, 2024).
cancer (continued). "It was found that ARID1A-deficient OCCC cells are often accompanied by low expression of SLC7A11, resulting in low basal GSH levels and weakening the cancer cells' resistance to oxidative stress, leading to apoptosis." (PMID 38347608, 2024). "ARID1A-deficient cancer cells are vulnerable to the loss of ARID1B, such that a concomitant loss of ARID1A and ARID1B disturbs enhancer dynamics at growth promoting loci." (PMID 38390898, 2024). "In the search for key genes in driving the progression and drug resistance of ARID1A-mutated NSCLC, we analyzed publicly available RNA-sequencing data acquired using different types of cancer cells with ARID1A ablation." (PMID 38229120, 2024). "Overall, our data suggest that some ARID1A-deficient cells maintain elevated levels of KEAP1, perhaps as a mechanism to sustain the growth of these cancer cells." (PMID 39272807, 2024). "We then screened an anticancer metabolism compound library consisting of 237 cancer cellular metabolism-related compounds using ARID1A-isogenic cells." (PMID 38811536, 2024). "The correlation between mutations in ARID1A, a gene implicated in chromatin remodeling, and improved outcomes after ICB therapy is well-documented across various cancer types including EC." (PMID 39902047, 2024). "Samples were re-clustered independently of their Arid1a status, allowing for an unbiased grouping solely based on gene expression similarities and the hallmarks of cancer." (PMID 39123453, 2024). "Nowadays, a diverse range of compounds holds potential benefits in ARID1A-altered cancers, including immune checkpoint blockade (PDL-1) and inhibitors of mTOR, EZH2, histone deacetylases, ATR, and/or PARP." (PMID 38391958, 2024). "Studies also demonstrated the role of ncRNAs regulating Arid1a expression and their involvement in different cancers." (PMID 39123453, 2024). "The results of this study are contrary to previous reports that ARID1A is useful as a biomarker for predicting the response to ICI therapy in other types of cancer." (PMID 38893118, 2024). "ARID1A loss activated NRF2 signaling in head and neck squamous tumors, confirmed using another cancer dataset." (PMID 38358974, 2024). "For example, a higher mutation rate of ARID1A, a tumor suppressor gene that is relevant to the MSI feature of cancers, was found in the TLS-high group." (PMID 38519621, 2024). "PLAU was identified as a common gene that was induced in different cancer cells upon ARID1A depletion." (PMID 38229120, 2024). "ARID1A, a component of the SWI/SNF chromatin-remodeling complex, is frequently mutated in various cancer types and has emerged as a potential therapeutic target." (PMID 38811536, 2024). "ARID1A is the core DNA-binding subunit of the BAF chromatin remodeling complex and is mutated in about 8% of all cancers." (PMID 39272807, 2024). "Up to 25% of human cancers carry mutations in at least one of nine SWI/SNF subunit genes including SMARCA1 and 2, SMARCB1, ARID1A/B, PBRM1, and ARID2." (PMID 38085333, 2024). "The binding of the macrolactam inhibitor, BD98, phenocopied some features of ARID1A/ARID1B loss and synergized with ATR inhibitors to kill a diverse array of cancer cells." (PMID 38390898, 2024). "ARID1A, a member of the SWI/SNF family can interact with EZH2 to inhibit IFN-responsive gene expression in cancer cells whose mutations can shape the cancer immune phenotype and immunotherapy." (PMID 38461299, 2024). "For the two patients with cancerous progression, the first patient was diagnosed as TVA mixing with carcinoma at the initial time and contained somatic mutations including APC, KRAS, and ARID1A." (PMID 39554798, 2024). "ARID1B, a paralogue of ARID1A, is among the top genes first identified that are preferentially required for the survival of ARID1A-mutant cancer cells." (PMID 36980292, 2023). "More than half of the patients with ARID1A+ cancer have a high TMB (≥ 20 mut/Mb), with 12 (48%) showing stability of the microsatellite system." (PMID 37711591, 2023).
cancer (continued). "The high frequency of ARID1A alterations in human cancers has highlighted its significance in tumorigenesis." (PMID 36890819, 2023). "A Phase II clinical trial (NCT02576444, OLAPCO) is currently ongoing for olaparil combination therapy in cancer patients with PTEN, PIK3CA, AKT, or ARID1A mutations or other mutations that lead to dysregulation of the PI3K/AKT pathway." (PMID 37096801, 2023). "As angiogenesis is one of the crucial carcinogenic features in many cancers, we thus attempted to investigate the effects of knockdowns of ARID1A and its interactor on transcription of angiogenesis-related genes." (PMID 38017409, 2023). "It's worth noting that the influence of ARID1A on immune cells can vary across different cancer types." (PMID 38041544, 2023). "EZH2-targeted inhibitors based on synthetic lethal effects play an essential role in ARID1A mutant cancers." (PMID 38008753, 2023). "There needs to be more research on how EZH2 inhibitors and ICB work together to treat ARID1A mutant cancer." (PMID 38008753, 2023). "ARID1A is the most frequently mutated SWI/SNF subunit in different tumors, and cancer-related mutations are spread across almost all regions of the ARID1A gene." (PMID 37175555, 2023). "In ARID1A mutant tumor cells, the loss of ARID1B leads to the loss of enhancer structure and changes in chromatin accessibility, making it challenging for cancer cells to survive." (PMID 38008753, 2023). "Since cancer-driver mutations (KRAS, ARID1A, PIK3CA) are similar in deep lesions and endometriomas, tumorigenesis results from additional factors." (PMID 36979957, 2023). "ARID1A and ARID1B are frequently co-mutated in cancer, but ARID1A-deficient cancers retain at least one functional ARID1B allele." (PMID 36844227, 2023). "In recent years, ARID1A and ARID1B co-mutations have been found in various cancers, but at least one functional allele has survived." (PMID 38008753, 2023). "The prognostic impact of ARID1A alterations or expression on cancer patients’ survival remains debated." (PMID 37711591, 2023). "ARID1A deletion changes the cancer precursor spectrum from PanIN to IPMN and accelerates the onset of invasive cancer." (PMID 36874143, 2023). "Consistently, a recent study of 3403 patients receiving ICB therapy across nine distinct cancer subtypes revealed ARID1A alterations as a biomarker for longer progression-free survival (PFS) after immunotherapy." (PMID 36980292, 2023). "PROTAC drugs targeting ARID1A can effectively degrade ARID1A in cells and affect its function, which will play a very good curative effect in the field of cancer therapy." (PMID 36770884, 2023). "The mechanism of action of ARID1A in cancer has been mainly attributed to its chromatin remodeling function within the SWI/SNF complex, leading to aberrant cell proliferation, differentiation and apoptosis that have tumorigenic consequences." (PMID 36980292, 2023). "We further show that drug sensitivity was impaired by increased cellular levels of ARID1A protein not only in CCOC, but in endometrial, colon, and HGSOC cells warranting further investigation of this combination in other cancer types with ARID1A loss." (PMID 37841875, 2023). "ARID1A mutant cancer cells showed an elevated basal level of reactive oxygen species (ROS) owing to aberrant metabolism." (PMID 37238613, 2023).